RNU6-1270P (RNA, U6 small nuclear 1270, pseudogene)
Gene: Small nuclear RNA gene on chromosome 3 (73,241,789 to 73,241,896, reverse strand). Ensembl gene ENSG00000252937.
Homologues: Orthologues: chimpanzee U6 (99% identical), macaque U6 (91% identical). Paralogues in human: RNU6-949P (92% identical), RNU6-1060P (90% identical), RNU6-19P (90% identical), RNU6-12P (89% identical), RNU6-13P (89% identical), RNU6-21P (89% identical), RNU6-24P (89% identical), RNU6-31P (89% identical), RNU6-32P (89% identical), RNU6-33P (89% identical), RNU6-672P (89% identical), RNU6-1 (88% identical), and 1283 more.